RN7SKP275 (RN7SK pseudogene 275)
Gene: Miscellaneous RNA gene on chromosome 4 (5,458,581 to 5,458,881, reverse strand). Ensembl gene ENSG00000201496.
Homologues: Orthologues: chimpanzee 7SK (99% identical), guinea pig 7SK (59% identical). Paralogues in human: 7SK (76% identical), RN7SKP180 (75% identical), RN7SKP79 (75% identical), RN7SKP203 (75% identical), RN7SKP176 (75% identical), RN7SKP78 (75% identical), RN7SKP162 (74% identical), RN7SKP102 (74% identical), RN7SKP217 (74% identical), RN7SKP226 (74% identical), RN7SKP33 (74% identical), RN7SKP47 (74% identical), and 284 more.